IGF1 (insulin like growth factor 1)
Diseases named in the same sentence as IGF1 in open-access papers (continued):
Sharing a sentence is not in itself a finding about the gene and the disease.
osteoarthritis (continued). "CILP1 can inhibit the response of insulin-like growth factor 1 (IGF-1) in chondrocytes, thereby impacting cell growth and repair, indirectly promoting hyperphosphatemia in aging and osteoarthritis, and increasing expression in early osteoarthritis patients." (PMID 38136386, 2023). "In osteoarthritis, insulin-like growth factor-1 (IGF-1) is significantly increased." (PMID 35607585, 2022). "Increased serum IGF-1 plays a critical role in higher osteoarthritis incidence." (PMID 36078169, 2022). "In this review, we explore evidence suggesting that Cytl1 may be involved in the regulation of chondrogenesis, cartilage homeostasis and osteoarthritis progression, accompanied by the modulation of Sox9 and insulin-like growth factor 1 expression." (PMID 31089746, 2019). "Insulin-like growth factor (IGF)-1 is a key factor in bone homeostasis and could be involved in bone tissue sclerosis as observed in osteoarthritis (OA)." (PMID 17129375, 2006). "Thus, a research gap exists concerning the specific impact of IGF-1 levels on different types of OA and whether osteoarthritis influences IGF-1 levels." (PMID 39050250, 2024). "Therefore, IGF-1 is expected to be effective as a therapeutic agent for osteoarthritis." (PMID 35948948, 2022). "The lack of observational evidence for an association between IGF-1 and knee OA is consistent with a previous case–control study (Framingham Osteoarthritis Study) of both incident and progressive radiographic knee OA, and a cross-sectional analysis in the Baltimore Longitudinal Study of Aging." (PMID 33027520, 2021). "Insulin-like growth factor-1 (IGF-1) has the potential to be used for osteoarthritis (OA) treatment but has not been evaluated in clinics yet owing to toxicity concerns." (PMID 35858920, 2022). "Given the known positive effects of both GH/IGF-1 axis and SST on cartilage repair, pain and function in the knee, we hypothesized that REG-O3 could be a disease-modifying osteoarthritis drug (DMOAD) for knee osteoarthritis (OA)." (PMID 32287299, 2020). "This study aimed to determine the collagen type II (COL2) and SOX9 expression in interleukin growth factor (IGF-1)-induced Wharton’s Jelly mesenchymal stem cells (WJMSCs) and the level of chondrogenic markers in co-culture IGF1-WJMSCs and IL1β-CHON002 as osteoarthritis (OA) cells model." (PMID 30140415, 2018).
dwarfism (46 papers, 2008 to 2025). "As we know, in mammals IGF-1 contributes to growth and body weight gain, while its insufficient production is associated with dwarfism." (PMID 40397066, 2025). "As a result of the GHR mutation there is a drastic reduction in IGF1 biosynthesis in the liver and, probably, other extrahepatic tissues, with ensuing dwarfism." (PMID 35283485, 2022). "In a murine model, knockout of the IGF1 gene led to infertility and dwarfism, underlying the influence of IGF1 already during the embryonic phase." (PMID 35626647, 2022). "In fact, IGF1 functions as a growth hormone and IGF1 deficiency is linked to dwarfism in mice and humans." (PMID 35741102, 2022). "LS is caused by the mutation or deletion of the GHR gene, or post-receptor pathways, leading to congenital IGF1 deficiency and dwarfism." (PMID 34204736, 2021). "Ames and Snell dwarf mice are characterized by IGF-1 deficiency in development which results in dwarfism, altered metabolism, reduced myocyte size, cardiac atrophy, and deregulated cardiac contractility profiles." (PMID 33807089, 2021). "Human insulin-like growth factor 1 (IGF-1) homozygous deficiency is an ultrarare disease associated with dwarfism, mental retardation, and syndromic sensorineural hearing loss (SNHL)." (PMID 34359856, 2021). "In humans, IGF-1 deficiency causes dwarfism and mutations in the Igf1 gene cause growth failure in utero, microcephaly, and mental retardation postnatally." (PMID 30808767, 2019). "Next, the skeletal phenotypes of IGF-1-deficient animals are described in both embryonic and postnatal stages of development, which include severe dwarfism and an undermineralized skeleton." (PMID 23382729, 2013). "Laron syndrome (LS) is a form of human dwarfism associated with the Gh-Igf1 axis." (PMID 37767364, 2023). "Additionally, the Zdbf2 growth reduction diverges from GH-related dwarfism: Gh-deficient mice grow normally until 10dpp, after which only they exhibit general growth impairment with reduced levels of circulating IGF-1." (PMID 35049495, 2022). "Severe IGHDIA with extremely low levels of circulating IGF1 could exhibit reasonable similarities with Laron's dwarfism, where a mutation in GH receptor abolishes the effect of GH on IGF1 production." (PMID 24683479, 2014). "IGF-1 is an important biomarker for the assessment of growth abnormalities such as growth retardation or dwarfism in children and adolescent populations." (PMID 40538800, 2025). "SRC-3 null mice displayed delayed puberty, slowed mammary gland growth, reproductive malfunction, and dwarfism due to alterations in the IGF-1 (insulin-like growth factor 1) signaling pathway." (PMID 37958417, 2023). "IGF-1 has been approved in many countries for the treatment of dwarfism and reportedly produces antidepressant and anxiolytic effects in obese postmenopausal women." (PMID 35577782, 2022). "This will aid in more comprehensively analyzing the effect of high-dose rhGH treatment in patients with idiopathic dwarfism, as well as its impact on IGF-1 and IGFBP-3 levels." (PMID 35634620, 2022). "Our objective was to analyze and compare the clinical effects of different doses of rhGH in the treatment of idiopathic dwarfism and its effects on the levels of IGF-1 and IGFBP-3." (PMID 35634620, 2022). "The dosage and duration of the treatment in the studies on patients with RTT were selected on the basis of the regimen of IGF1 treatment for dwarfism." (PMID 32756423, 2020). "These individuals are characterized by severe dwarfism, due to very low GH and IGF-1 levels, increased adiposity, and increased insulin sensitivity." (PMID 33312162, 2020). "IGF-1 is currently approved by the Food and Drug Administration (FDA) for the treatment of short stature due to primary IGF-1 deficiency (Laron’s Dwarfism)." (PMID 25685306, 2014). "The focus of this study was on insulin-like growth factor-1 (IGF-1), which has been used for the treatment of insulin-resistant diabetes and dwarfism." (PMID 25406953, 2014).
dwarfism (continued). "As has been shown in multiple studies of dwarfism, mice with reduced levels of GH and IGF1 are insulin sensitive." (PMID 23077600, 2012). "The Igf1r+/− mouse model has allowed us to study the effect of just reduced IGF-1 signaling on lifespan/aging from the many other pathways that are affected by dietary restriction and dwarfism." (PMID 22132081, 2011). "Similarly, GHR-deficient mice (Laron mouse) exhibit severe postnatal growth retardation, proportionate dwarfism, and decreased serum IGF-1 levels." (PMID 40598150, 2025). "Since mutation in TMEM263 is linked to human skeletal dysplasia and dwarfism in chicken, and TMEM263 is also a GWAS candidate gene for BMD, we speculated that TMEM263 may be a novel regulator of the GH/IGF-1 axis." (PMID 38241182, 2024). "Several reports have documented dwarfism resulting from defective Igf1 secretion due to Ghr dysfunction.Ghrknockout experiments in mice and pigs have successfully replicated the LS phenotype, emphasizing the crucial role of Ghr in determining mammalian body size." (PMID 37767364, 2023). "Mutations in GH and IGF-1 genes are also important when studying body dwarfism, because the mutations of both genes may play roles altering the GH–GHR–IGF-1 axis signaling transduction." (PMID 29748515, 2018). "Dwarfism is characterized by normal or elevated serum GH and low levels of IGF-1." (PMID 29748515, 2018). "The growth hormone (GH)–IGF-1 axis is well known to promote development and growth in vertebrates; by contrast, reduced GH–IGF-1 signaling results in dwarfism but extends the lifespan and retards the aging process." (PMID 32630045, 2020). "Since Laron’s first description of dwarfism in humans due to defects in the GHR, an enormous amount of progress has been made to understand how GH and IGF-1, as well as their binding proteins, receptors, and signaling pathways, contribute to linear growth." (PMID 38241182, 2024). "Despite the variability in the mutations observed, the phenotypic consequences are remarkably similar, i.e., dwarfism, lack of GH signaling and undetectable, or extremely low, IGF1 values." (PMID 35283485, 2022). "Strong epidemiological evidence shows that people without GHR (Laron dwarfism) live healthy normal lives despite low IGF-1 levels." (PMID 33312162, 2020).
neuroblastoma (46 papers, 2006 to 2025). Neuroblastoma (NB) is the most common solid, extracranial childhood tumor. "The binding of IGF1 to IGF1R has been implicated in regulating neuroblastoma metastasis to bone, highlighting the multifaceted role of the IGF1/IGF2‐IGF1R axis in disease progression and dissemination." (PMID 40679030, 2025). "We previously identified neuronal leucine-rich repeat 1 (NLRR1) as a positive regulator of EGF and IGF-1 signals in high-risk neuroblastoma cells." (PMID 34277416, 2021). "Previous studies have shown the capability of IGF-1 to modulate Ca2+ channels in neuroblastoma cells and modify the electrophysiological properties of dorsal column nucleus (DCN) neuron in the brain stem." (PMID 33551743, 2020). "We also observed CLASP2 relocalization to MT plus-ends upon insulin or IGF-1 treatment in neuroblastoma cells or neurons, respectively." (PMID 30787869, 2019). "In the previous study, the result of knockdown experiments using small interfering RNA (siRNA) in a neuroblastoma cell line (SH-SY5Y) suggested that GAREM2 is a regulator of IGF-1-induced neurite outgrowth." (PMID 31718706, 2019). "IGF-1 also has ameliorating effects on apoptosis of human neuroblastoma cells with glucose deprivation." (PMID 33817186, 2019). "In neuroblastoma cell lines, overexpression of miR-126 impairs IGF-1 induced cell proliferation and increases sensitivity to the neurotoxic agent 6-OHDA, while inhibition of miR-126 enhances the protective effects of IGF-1 against cell death." (PMID 30618607, 2018). "IGF-1 has been described as affecting neuroblastoma growth and metastasis, including actin cytoskeletal rearrangement, enhanced cell motility, and neurite outgrowth." (PMID 24349301, 2013). "It has been previously reported that insulin-like growth factor 1 results in rapid translocation of P-Akt into mitochondria of neuroblastoma and human embryonic kidney cells." (PMID 19844585, 2009). "Work by others has demonstrated that IGF-1 can activate CaMKII signaling pathways in human neuroblastoma and rat hippocampal neurons, and this occurs due to increased cystolic Ca2+ from the PLC-γ/IP3 activity." (PMID 18604269, 2008). "AAH and Humbug are over-expressed in SH-Sy5y neuroblastoma cells, and their mRNAs are regulated by insulin/IGF-1 signaling through Erk MAPK, PI3 kinase-Akt, and Cdk-5, which are known mediators of cell migration." (PMID 17156427, 2006). "Initial studies characterized the signaling pathways that are likely to mediate insulin and IGF-1 signaling in SH-Sy5y neuroblastoma cells." (PMID 17156427, 2006). "Earlier work in cell culture demonstrated that MAPK phosphorylates ERα at S118 following IGF-1 treatment, and recent work from our laboratory in a neuroblastoma cell line supports the role of neuroestrogens in activating the MAPK pathway in conjunction with IGF-1R." (PMID 36261268, 2022). "Kao, for instance, has shown IGF-1 to block the formation of α-syn aggregates and suppress α-syn cytotoxicity in dopamine-treated SH-SY5Y cells; Chung and colleagues hypothesized α-syn to play an important role in IGF-1 signaling activation in the neuroblastoma cell line." (PMID 35454152, 2022). "Increased PAD prevalence in prolactinomas and somatoprolactinomas has been associated with increased mRNA targeting of oncogenes HMGA, Insulin-like Growth Factor 1 (IGF-1), and Neuroblastoma MYC Oncogene (N-MYC) by miRNAs, which may yield insight into the etiology of the affected tumor subtypes." (PMID 31139150, 2019). "The IGF1R pathway is aberrantly activated by autocrine and paracrine signaling loops in neuroblastoma tumors through the release of IGF1 and IGF2, ligands for IGF1R, from the neuroblastoma and stromal cells within the tumor." (PMID 39001383, 2024).
neuroblastoma (continued). "Using a human SH-SY5Y neuroblastoma cell line overexpressing SNCA, Kao showed that insulin-like growth factor 1 (IGF1) application rescues α-syn toxicity and aggregation." (PMID 38596238, 2023). "As for the neuroblastoma SH-SY5Y cell line, it has been reported that basic FGF (bFGF) and IGF-1 are the two most potent mitogens." (PMID 34638536, 2021). "For instance, ER in the nucleus can be induced by insulin-like growth factor 1 (IGF1) and lead to MAPK signaling activity in the neuroblastoma cells via the genomic pathway." (PMID 32150843, 2020). "Several reports indicate that growth factors, such as IGF-1 and PDGF, and integrins can stimulate neuroblastoma cell motility." (PMID 19077250, 2008). "We focused on the ALK, IGF1, WNT, EZH2/PRC2, BET, CDK7, and CDK12/13 signaling pathways since they have been shown to be important during the normal development of sympathoadrenal cells and/or involved in neuroblastoma tumorigenesis." (PMID 35681734, 2022). "In addition, insulin-like growth factor-1 (IGF-1), whose secretion from diverse tissues including the liver is regulated by growth hormone (GH) in vivo, shows well characterised survival effects both for doxorubicin challenged cardiomyocytes and for neuroblastoma cells under hyperosmotic stress." (PMID 26057745, 2015). "We treated AKT2 silenced neuroblastoma cells with or without GRP (100 nM) for 2 h after serum-starvation overnight, and IGF-1 (100 nM) was used as positive control." (PMID 23468863, 2013).
Rett syndrome (46 papers, 2011 to 2025). A severe neurodevelopmental disorder affecting the central nervous system. "IGF-1 is currently being tested in clinical trials conducted on subjects with Rett syndrome, Fragile X syndrome, and SHANK3 deficiency." (PMID 40434434, 2025). "In two of the single gene disorders associated with ASD, Insulin Growth Factor (IGF-1) is a new treatment that has been tested in Rett syndrome and Phelan-McDermid syndrome (Chromosome 22 deletion syndrome)." (PMID 24999471, 2014). "On the other hand, Trofinetide, a small synthetic analog tripeptide derivative of IGF-1, was recently approved in the United States for the treatment of a rare childhood neurodevelopmental disorder, Rett syndrome, where administration is associated with significant symptom improvements." (PMID 37963901, 2023). "The compound’s exceptional ranking reflects optimal integration of network proximity to IGF1 pathway genes with favorable physicochemical properties and established CNS penetration in Rett syndrome populations." (PMID 41155297, 2025). "Recent phase III clinical studies have shown that IGF1 analogs can improve autism-like behaviors in patients with Rett syndrome." (PMID 39376742, 2024). "In March 2023 an IGF-1 derivative was approved as the first drug for treating Rett syndrome, an ASD-related neurodevelopmental disorder, to improve fundamental symptoms such as social communication." (PMID 39188438, 2024). "The United States Food and Drug Administration (FDA) has awarded Fast Track and Orphan Drug designation to the IGF-1 for treating Rett syndrome, also known as (RS) and Fragile X syndrome." (PMID 39329976, 2024). "The IGF-1 has begun to demonstrate its effectiveness in alleviating symptoms also in children with Rett syndrome, a genetic condition that has several clinical similarities to ASD." (PMID 39329976, 2024). "It has been discovered that levels of IGF-1 are reduced in the hippocampus of Rett syndrome mouse model." (PMID 38716113, 2024). "Trofinetide is a synthetic analog of glycine–proline–glutamate, the N-terminal tripeptide of the insulin-like growth factor 1 protein, and has demonstrated clinical benefit in phase 2 studies in Rett syndrome." (PMID 37291210, 2023). "Four weeks of IGF-1 therapy to 12 female Rett syndrome patients improved mood stability, apnea and anxiety in a phase 1 clinical trial." (PMID 35298717, 2022). "In fact, IGF-1 has been useful in Rett syndrome (RTT) and in Phelan–McDermid Syndrome, both neurodevelopmental ASDs10,54–55." (PMID 35962006, 2022). "In this study, we used signal analyses of noninvasive resting state EEGs to characterise cortical network profiles in patients with Rett Syndrome treated with IGF1 and untreated patients (controls)." (PMID 32756423, 2020). "Administration of recombinant human IGF-1 is effective in reversing autonomic dysfunction in Rett syndrome." (PMID 30524358, 2018).